CD4 (CD4 molecule)
Diseases named in the same sentence as CD4 in open-access papers (continued):
Sharing a sentence is not in itself a finding about the gene and the disease.
cancer (continued). "MIR100HG was significantly correlated with the expression of CD200, CD274 and CD276 in pan‐cancers and was significantly associated with the abundance of central memory CD8 T cells, effector memory CD4 T cells and effector memory CD8 T cells in pan‐cancers." (PMID 33797188, 2021). "In the following years, it was reported that CD4+ CD25+ T cells are increased in blood and tumors of patients with a variety of cancers, including breast, pancreatic, ovarian, and non-small-cell lung cancer (NSCLC)." (PMID 34632244, 2021). "Further studies on ferroptosis-induced CD4+ T cell activation will provide a new perspective on the complexity of the TME and diverse strategies for cancer immunotherapy." (PMID 34966745, 2021). "Some studies have suggested that the presence of CD4+ and CD8+ cells were correlated with improved survival in patients with certain cancers." (PMID 34257554, 2021). "Extracellular ATP, released in TME by cancer cells and infiltrating inflammatory cells, interacts with P2X7R expressed by DCs to stimulate IL-1β release, which in turn increase CD4+ and CD8+ T cells, mediating antitumor responses." (PMID 33806300, 2021). "HLA-DR-restricted epitopes with embedded HLA class I-binding peptides, to induce both CD4+ and CD8+ T cell responses, are widely used for anti-cancer as well as anti-viral immunotherapy." (PMID 33723016, 2021). "CD4+CD25+ regulatory T cells decrease the antitumor immune response and inhibit the curative effect of cancer immunotherapies." (PMID 34063848, 2021). "It has been reported that immune cells, including natural killer cells, CD4+ and CD8+T-cells, TAMs, and dendritic cells, and others, are detected in cancer tissues, including HCC." (PMID 34093635, 2021). "The estimated score of CD8+ T cells, CD4+ central memory T cells (CD4+ Tcm), and Th1 cells were increased significantly in MTDH-low expression patients across diverse cancer types." (PMID 34622157, 2021). "With 10 identifiers, we observed that these genes interacted with stemness genes such as SOX-2 and NANOG, genes important in cancer pathways such as STAT3, CTNNB1, EGFR, TNF, and CASP3, and immune genes such as IL2 and CD4." (PMID 34685742, 2021). "It was demonstrated that also ILC2, double-positive CD4+ CD8+ T cells, and cancer-initiating cells secrete this cytokine." (PMID 35008550, 2021). "MKI67 was also related to CD4+ T cell infiltration degrees in 22 cancers, CD8+ T cell infiltration degrees in 19 cancers, DC infiltration degrees in 25 cancers, neutrophil infiltration degrees in 24 cancers, and macrophage infiltration degrees in 17 cancers." (PMID 34724892, 2021). "The ChIP analysis on the PD-L1 promoter region indicated that the BRM recruitment in control CD4+ T cells was replaced by BRG1 and EZH2 in CD4+ T cells strongly exhausted by cancer cells." (PMID 34439305, 2021). "Moreover, our study is supported by another group from The Scripps Research Institute, which showed that CCR5 expression in both CD4+ and CD8+ T cells was necessary to activate cancer immune response that might have implications for cancer treatment in patients with CCR5 deficiency." (PMID 34717291, 2021). "Our analysis results showed that ASB16-AS1 was positively correlated with B cells, T cells CD4+ and T cells CD8+ in most cancer types, and negatively correlated with dendritic cells, macrophages and neutrophils in some cancer types, especially neutrophils." (PMID 34709970, 2021). "Cluster 10_Mitotic Treg was enriched for ‘cell cycle pathway’ while cluster 7_CD4+ TEM was enriched for ‘PD‐L1 expression and PD‐1 checkpoint pathway in cancer’, indicating the phenotype of T‐cell exhaustion." (PMID 33513276, 2021). "While the treatment has been effective overall during the cART era, the present study also indicated that patients with nadir CD4 < 200 (cells/μL) accounted for 45.6 and 62.8% of anal HSIL and cancer, respectively." (PMID 33596943, 2021).
cancer (continued). "CD4+ and CD8+ T cells identify cancer cell-related antigens and play a significant role in cancer immunotherapy." (PMID 33536348, 2021). "Vaccine-reactive T cells comprised CD4+ and CD8+ T cells with activity against IDO- and PD-L1-expressing cancer and immune cells." (PMID 34887574, 2021). "On the other hand, in an attempt to control the tumorigenesis process, CD4+ T-regulatory cells secrete TNF-α, a molecule that shows a dual role in immunomodulation, being also expressed by cancer cells, acting as an autocrine growth factor." (PMID 33644151, 2021). "First, we analyzed the scores of 6 types of immune cells (B cell, CD4+ T cell, CD8+ T cell, neutrophil cell, macrophage cell, and dendritic cell) from 33 cancer types through the TIMER database." (PMID 34737838, 2021). "In general, the expression of receptor tyrosine kinases (RTKs) in cancer cells can activate the STAT3/5 signaling pathway, which promotes the secretion of TH2 cytokines and then promotes the survival of CD4+ Foxp3+ Tregs." (PMID 34062992, 2021). "HHLA2 can inhibit the function of CD4 and CD8 T cells, and blocking HHLA2 can enhance the proliferation and activation of T cells, which is helpful for cancer immunotherapy." (PMID 34660693, 2021). "Although, the majority of cancer immunotherapies center around exploiting the cytotoxic properties of CD8+ T cells, the potential role of CD4+ T helper cells remains ill-defined." (PMID 34548096, 2021). "CD4+ T helper cells and the CD8+ cytotoxic T cells are the main effector cells that target cancer cells by controlling the humoral and cell-mediated response through the production of cytokines, perforin, and granzymes." (PMID 32808188, 2021). "The peptide sequence length was inspired by previous work in cancer neoantigen vaccination which has demonstrated strong CD8+ and CD4+ responses using 27mer peptides." (PMID 34127050, 2021). "The results showed that ASB16-AS1 was positively correlated with B cells, T cells CD4+ and T cells CD8+ in most cancer types, and negatively correlated with dendritic celsl, macrophages and neutrophils in some cancer types (>14), especially neutrophils." (PMID 34709970, 2021). "Based on this, individuals in the active TB group were enriched for CD4+ and CD8+ cells expressing CD69 compared with previous TB or cancer controls, reaching significance for CD8+ T cells." (PMID 33848273, 2021). "In certain cancers, high numbers of CD8 and CD4 cells in the TME correlate with better prognosis disease." (PMID 33773029, 2021). "This leads to activation of CD4+ and CD8+ T cells for elimination of cancer cells, and it establishes the feasibility to combine cancer vaccine with HMAs to enhance vaccine immunogenicity." (PMID 33718188, 2021). "A recent meta-analysis demonstrated that high-density TILs, CD3+ TILs, CD4+ TILs, CD8+ TILs and CD20+ TILs in cancer nests were good prognostic markers for NSCLC patients." (PMID 34631307, 2021). "For example, bevacizumab therapy promotes infiltration by CD4+ and CD8+ T cells and stimulates PD-L1 expression in carcinomas." (PMID 34572851, 2021). "The densities of CD4+ T-cells and CD8+ T-cells in the carcinoma and the stromal areas of the brain metastases were positively correlated with OS by linear regression models." (PMID 34647108, 2021). "The prognostic value of carcinoma versus stromal lymphocytic infiltration has been reported in NSCLC, with only high density CD4+/CD8+ stromal lymphocyte infiltration being an independent positive prognostic indicator for patients with resected NSCLC." (PMID 34647108, 2021). "It was discovered that the WDR4 levels were significantly correlated with the infiltration levels of CD4+ T and CD8+ T cells in 21 types of carcinoma, B cells in 14 types, neutrophils in 15 types, macrophages in 14 types, and dendritic cells in 19 types." (PMID 34282052, 2021).
cancer (continued). "Inversely, there were elevated levels of the following T‐cell percentages in cancer patients compared to those in healthy controls: memory CD4+/CD4+, CD8+ T cells, HLA‐DR/CD8+, CD8+ CD38+/CD8+, and CD4+/CD8+." (PMID 32459060, 2020). "The levels of resting CD4 memory T cells, M2 macrophages, and CD8 T cells were high in many cancer types, while gammadelta T cells, naive CD4 T cells and memory B cells constituted a low proportion of the total cells." (PMID 32294976, 2020). "On the other hand, Treg subset of CD4+ T cells have been shown to inhibit cytotoxic functions of CD8+T cells, support B cell growth, and promote cancer progression." (PMID 33086518, 2020). "After five days co-culturing naïve T cells withnormal- and cancer-ASCs, CD45RA+ T cells wereinvestigated in the population of CD4+CD25+FOXP3+and CD4+CD25-FOXP3+ cells." (PMID 31721539, 2020). "The development of CD4 T cell therapy for HIV infection requires approaches different from those used for other viruses and cancers." (PMID 32462053, 2020). "In contrast, a higher percentage of memory CD4+/ CD4+ T cells (P < .001), CD8+ HLA‐DR/ CD8+ T cells (P < .001), CD8+ CD38+/ CD8+ T cells (P < .001), and the CD4+/ CD8+ ratio (P < .001) were observed in cancer patients compared to healthy controls." (PMID 32459060, 2020). "Mean ± SEM percentageof T cells with CD4+CD25+FOXP3+Helios+ phenotypewere 15.59 ± 4.6%, 12.63 ± 3.6%, and 5.90 ± 2.6% inthe presence of cancer-ASCs and normal-ASCs and inthe control group, respectively." (PMID 31721539, 2020). "Helios+ T cells, in the population of CD4+CD25-FOXP3+, were increased in the presence of normal-ASCs and cancer-ASCs." (PMID 31721539, 2020). "CD4+ regulatory T cells (Tregs) expressing transcription factor FOXP3 are highly immunosuppressive, and in malignant tumors, they promote cancer progression by suppressing antitumor immunity." (PMID 33614479, 2020). "We first compared the immune infiltration determined by the quantitative analysis of different immune markers (CD3, CD4, CD8, PD1, PD-L1, FoxP3, CD45) between hereditary and sporadic MSI cancers." (PMID 32512823, 2020). "A Cochrane review of five RCTs using Ganoderma lucidum as complementary cancer therapy showed that patients in the verum group had increased natural killer cell activity and increased levels of CD3, CD4 and CD8, leukocytes, and CD4/CD8 ratio." (PMID 33424591, 2020). "There are memory CD4+ T cells specific to some Bacteroides species in the spleens of anti-CTLA-4 mAb treated mice and in the blood of ipilimumab-treated cancer patients." (PMID 32221812, 2020). "The immune response of cancer cells depends on the presence of neoepitopes and enrichment of CD8+ T cells, CD4+ T cells, and antigen-presenting cells (APCs) such as dendritic cells." (PMID 32850350, 2020). "Jurkat HIV-1 T cells (a cellular model of HIV latency), HCT116 cells (a cancer cell line used during development of VOR), or uninfected primary resting CD4 T cells were pulsed with 340 nM VOR for 6 h." (PMID 32295913, 2020). "Flow cytometry was performed to identify and collect the cancer cells marked by EPCAM, T cells marked by CD3D, CD8+ T cells marked by CD8A, and CD4+ T cells marked by CD4 in the GGN-ADC and SADC samples." (PMID 33083004, 2020). "Functionally, FoxP3+IL17A+ Tregs from sporadic CRC patients maintained their suppressive phenotype against CD4+ and CD8+ T cells but they were involved in cancer initiation by targeting epithelial cells in an IL17A-dependent manner." (PMID 32937953, 2020). "The CD4 and CD8 effector cells that identify and eliminate cancer cells play an essential role in cancer immunotherapy." (PMID 32477458, 2020). "CD4+ T-cell help and cytotoxic activity of CD4+ and CD8+ T-cells play an important role in eliminating infected cells and cancer cells." (PMID 32560243, 2020). "Murine dexosomes have been shown to be able to stimulate melanoma antigen-specific CD4+ and CD8+ T cells in vitro and generate anti-cancer immunity in vivo." (PMID 32765528, 2020).
cancer (continued). "Toll-like receptor (TLR) ligands are promising adjuvants for cancer immunotherapy, but TLR7/8 ligand Resiquimod has been shown to inhibit CD4 T-cell activation in a monocyte-dependent manner." (PMID 32183240, 2020). "Next, we investigated the correlation of the DC fraction with major anti-cancer immune cells, CD8+ and CD4+ memory T cells as well as immune function scores, IFN-γ, and CYT scores in the TCGA and METABRIC cohorts." (PMID 33198125, 2020). "It is well documented that a decrease in CD4+ and CD8+ populations occurred in the peripheral blood of patients suffering from different cancers." (PMID 32023984, 2020). "Our analyses further demonstrate that ACE2 expression has a significant correlation with the infiltrating levels of dendritic cells, CD4+ T cells, CD8+ T cells, mast cells, B cells, and NK cells in most cancers." (PMID 33195415, 2020). "We propose that monitoring CD4 T cell immunity against TERT is a simple and direct way to assess immune surveillance in cancer patients and a new way to predict the response to immune checkpoint inhibitors (ICPi)." (PMID 32630460, 2020). "CD4+ T cell counts and percentages of CD8+ HLA‐DR/CD8+ and CD8+ CD38+/CD8+ can be potential blood biomarkers of cancer progression." (PMID 32459060, 2020). "Accordingly, we found that SYNE3 expression was significantly correlated with dendritic cell, neutrophil, CD4 + T cell, macrophage, CD8 + T cell and B cell in 30, 30, 27, 26, 25, 25 and 22 types of cancer respectively." (PMID 32948197, 2020). "CD4+ T-cells had a FOXP3+ regulatory phenotype, occasionally as the minor population, as shown in other cancer models." (PMID 31959856, 2020). "The aspiration of neoantigen cancer vaccine design is to find approaches capable of eliciting both robust cytotoxic CD8+ T cell responses and CD4+ T cell help, the key to establishing memory." (PMID 33298945, 2020). "The BTLAhigh group recruited a high proportion of CD4+ T cells, CD8+ T cells, Th1 cells, dendritic cells, macrophage, NK cells, and Th2 cells in primary and metastatic SKCM tissues in the cancer immunity cycle." (PMID 33718105, 2020). "The sustained upregulation of PD-1 in CD4+ T cells and CD8+ T cells was one of the characteristic features of T cell exhaustion during chronic infection or cancer." (PMID 33552075, 2020). "We previously reported upregulated PD-1 expression on both CD4+ and CD8+ T cells obtained from cancer tissue in GC patients." (PMID 32131763, 2020). "Increased percentages of NK cells in cancer patients can be one reason why we see preferential increase in CD8+ T cells and lower ratios of CD4+/CD8+ T cells." (PMID 33230147, 2020). "The PD-1 expression levels on peripheral CD4+ T and CD8+ T cells were significantly elevated in samples from patients with cancer and CIN." (PMID 33552075, 2020). "CD4 T cells also act to stave off CD8 T cell dysfunction during repetitive antigen stimulation in persistent infection and cancer by mitigating generation of exhausted T cells (TEX)." (PMID 32971931, 2020). "Further, the specific ratios between Th1 and Th2, CD4+ and CD8+, and Th17 and regulatory T Cells (Tregs) are essential in a healthy system, but as cancer develops, these ratios are dysregulated." (PMID 32372963, 2020). "Earlier work studying the immune landscape of different cancers based on specific signatures that tell of immune function explains that neoantigen load is correlated to CD8+ T cells, M1 macrophages, CD4+ T cells, and lower T regs." (PMID 32117295, 2020). "In this regard, inducing multifunctional CD4+ and CD8+ T cells is critical to the success of various therapeutic cancer strategies." (PMID 33105813, 2020). "Telomerase therapeutic vaccines (with over 30 different peptides currently in clinical trials) also offer the potential to stimulate the killing of cancer cells by increasing the activity of telomerase-specific cytotoxic (CD8) and helper (CD4) T cells." (PMID 33297561, 2020).
cancer (continued). "The expression of CBXs were found to be significantly correlated with the infiltration of diverse immune cells, including six types of CD4+ T cells, macrophages, neutrophils, B cells, CD8+ T cells, and dendritic cells in CRC cancers." (PMID 33014884, 2020). "Abnormal levels of NK cell, CD8+ T cells, memory CD4+/CD4+, naïve CD4+/CD4+, CD8+ HLA‐DR/CD8+, CD8+CD38+/CD8+, and CD4+/CD8+ can be a potential blood biomarkers of cancer disease progression." (PMID 32459060, 2020). "The violin map showed that there were more intuitively resting memory CD4+ T cells, CD8+ T cells, and macrophages in cancer than in normal tissues, accounting for their increased proportions." (PMID 32228629, 2020). "Most cancer cell therapies have employed transfusion of autologous T-cells into patients, including CD8+ CTLs alone or combined with CD4+ helper (Th) cells, although NK or cytokine-induced killer cells and macrophages have also been used." (PMID 32937961, 2020). "Recent evidence suggests that major immune antitumor responses are driven by T CD4 and T CD8 cell reactivity against two classes of tumor-derived antigens: neoantigens and cancer germline antigen genes (CAGs)." (PMID 33282963, 2020). "Expression of CD3, CD4, FOXP3, and PD‐L1 TPS was significantly higher in OTSCC cases relative to non‐cancer cases." (PMID 32383556, 2020). "CTLA4, as a transmembrane protein expressed in activated CD4+ T and CD8+ T cells, has received a lot of attention for its interaction with cancer." (PMID 33117084, 2020). "CD4+ T‐cell counts and percentages of CD8+ HLA‐DR/ CD8+ and CD8+ CD38+/ CD8+ can predict the cancer progression." (PMID 32459060, 2020). "The comparison of healthy donors and HNSCC patients revealed lower PD-1 expression levels on CD4+ and CD8+ T cells from cancer patients compared to healthy donors by tendency that were significantly lower only after 72 h." (PMID 33053760, 2020). "To further confirm the expression of ARV7 and ARFL in PBMC we studied five subpopulations (CD4 and CD8 T-cells, B lymphocytes, T-natural killer cells [NK], and monocytes) isolated from PBMC of four non-cancer controls." (PMID 31947623, 2020). "In summary, this pan-cancer analysis demonstrated that increased ENO1 expression was correlated with poor prognosis and decreased immune infiltration levels in macrophages, CD4+ T cells, CD8+ T cells, and B cells in CESC and LUAD." (PMID 33643901, 2020). "It was previously showed in a mouse model of BC, that C5a/C5aR system facilitated metastasis in the lungs by creating a microenvironment favourable for cancer cells (by suppressing effector CD8+ and CD4+ T cell responses)." (PMID 32669478, 2020). "To this end, we have built a mathematical model of the major cell types that intervene in ICD, namely cancer cells, DCs, CD8+ and CD4+ T cells." (PMID 33281620, 2020). "CD4 and CD8 antibodies were injected 2 days prior to the injection of cancer cells, and every 5 days until the endpoint, and the efficiency of depletion was verified by FACS analysis." (PMID 33123539, 2020). "OX40 treatment has been reported to increase expression of ICOS on both CD4 and CD8 T-cells, and modulating this pathway can impact the therapeutic response to anti-OX40 antibodies in mouse models of cancer." (PMID 31959281, 2020). "The panel was based on a backbone mixture of dried antibodies (anti-CD3, anti-CD4, anti-CD8, anti-CD45RA, and anti-CCR7) to detect naïve/memory T cells, recognised as potential prognostic/predictive immunological biomarkers in cancer immunotherapies." (PMID 32322591, 2020). "Memory T cells (TM, CD4+/CD44+) are T cells that have had interaction with specific antigens or cancer, and are able to mount a strong and rapid response to the pathogen or cancer." (PMID 32372963, 2020). "The polarization of T cell, especially differentiation into CD4+ Th1 and CD8+CTL cells, is of particular interest to cancer immunotherapy." (PMID 32595493, 2020).